ZNF182 (zinc finger protein 182)
Description:
May be involved in transcriptional regulation.
Synonyms: KOX14; ZNF21; HHZ150; Zfp182
Tractability: PROTAC: ubiquitination databases record sites on it.
Gene: Protein-coding gene on chromosome X (47,974,851 to 48,004,375, reverse strand). Ensembl gene ENSG00000147118.
Subcellular location: Nucleus
Subcellular location (Human Protein Atlas): Nucleoplasm
Gene Ontology:
Molecular function: DNA-binding transcription factor activity, RNA polymerase II-specific; RNA polymerase II cis-regulatory region sequence-specific DNA binding; DNA binding
Biological process: regulation of transcription by RNA polymerase II; negative regulation of transcription by RNA polymerase II; regulation of DNA-templated transcription
Cellular component: nucleus; nuclear lumen
Homologues: Orthologues: chimpanzee ZNF182 (99% identical), macaque ZNF182 (98% identical), pig ZNF182 (93% identical), dog ZNF182 (91% identical), rabbit ZNF182 (91% identical), guinea pig ZNF182 (88% identical), rat Zfp182 (87% identical), mouse Zfp182 (85% identical). Paralogues in human: ZNF484 (53% identical), ZNF605 (52% identical), ZNF41 (51% identical), ZNF300 (51% identical), ZNF33B (51% identical), ZNF717 (51% identical), ZNF658 (49% identical), ZNF630 (49% identical), ZNF334 (48% identical), ZNF568 (48% identical), ZNF585B (47% identical), ZNF175 (47% identical), and 164 more.
Diseases named in the same sentence as ZNF182 in open-access papers:
ZNF182 is named in the same sentence as 3 diseases in open-access papers, as found by Europe PMC text mining. Sharing a sentence is not in itself a finding about the gene and the disease. The quoted sentences say what the papers report.
developmental delay (2 papers, 2015 to 2024). "A 335.4-kb duplication in the Xp11.2p11.3 region, which contains the C2H2 zinc finger proteins, ZNF81 and ZNF182, was identified in a patient showing developmental delays, autistic features, and growth and speech delays." (PMID 38830862, 2024). "In a comparative genomic hybridization (CGH) array analysis a duplication of SPACA5 (and ZNF81/ZNF182) has been described in a boy with developmental delay, autistic features, and growth and speech delay." (PMID 25984793, 2015).
ZNF182 also shares sentences with these, for which no sentence is quoted: speech delay (2 papers); tumour (1).